IL6 (interleukin 6)
Diseases named in the same sentence as IL6 in open-access papers (continued):
Sharing a sentence is not in itself a finding about the gene and the disease.
depression (continued). "We did not evaluate another key cytokine, IL6, in this study; however, we have previously reported that IL6 and IL10 expression increased in female patients with active medication refractory depression." (PMID 24826212, 2014). "Studies have shown that levels of interleukin (IL)-6 and C-reactive protein (CRP), and the immunologic complement component 4 (C4), but not C3, are significantly raised in patients with depression compared with controls." (PMID 23506529, 2013). "In particular, serum IL-18 levels, but not that of IL-6 or TNF-α, measured 1 and 7 days after stroke were higher in patients that later developed depression." (PMID 23675319, 2013). "However, it should be noted that for serum levels of TNFα there is an increasing trend and for levels of IL-6 there is a decreasing trend in the two subgroups of perimenopausal women with depression (treated and not treated with SSRIs) when compared to perimenopausal women without depression." (PMID 22490187, 2012). "We found significant correlations between fatigue, depression and anxiety on one hand, and TNF-α and sIL-2R, but not CRP or IL-6, on the other hand." (PMID 23082161, 2012). "After evaluation of depression level study group was divided into groups according to the mood status (A—without depression, B—mild depression, and C—severe depression), and serum concentration of TNF-α, sTNFs, leptin, and IL-6 were measured by ELISA." (PMID 19587822, 2009). "Unlike the widely studied proinflammatory cytokines (IL-6, TNF-α, and CRP), these markers are rarely investigated in psychiatric research, despite their potential as indicators of both the metabolic and inflammatory background of depression." (PMID 40507778, 2025). "Dysregulation of the HPA axis after MI and subsequent depression may be influenced by inflammatory factors, particularly Interleukin (IL)-12A and tumour necrosis factor (TNF)-α, but not IL-1β and IL-6." (PMID 41301929, 2025). "Compared with non-depressed individuals, patients with depression show elevated levels of proinflammatory cytokines, including interleukin-1(IL1), interleukin-6(IL6), and tumor necrosis factor-alpha(TNF-α), as well as the systemic inflammation biomarker C-reactive protein(CRP)." (PMID 41179571, 2025). "Previous studies have suggested that higher levels of several proinflammatory biomarkers such as C-reactive protein, IL-6 and TNF-α may be related to non-response to antidepressant drugs in people with major depressive disorder." (PMID 40624224, 2025). "However, whereas a more recent meta-analysis confirmed the finding of higher levels of CSF IL-6, no group differences regarding IL-8 and TNF-ɑ were seen when comparing patients with depression to healthy controls." (PMID 37016363, 2023). "A separate network analysis showed that higher IL-6 and CRP more strongly coincided with increased somatic symptoms (i.e. aches, pains, sleep issues) v. other depression nodes in Dutch adults with and without elevated depression." (PMID 35924730, 2023). "This intense stress can modulate changes in multiple pro-inflammatory cytokines, including interleukin-6 (IL-6) and tumor necrosis factor-α (TNF-α), leading to the appearance of depressive symptoms, such as sadness, lethargy, and lack of pleasure, and even to depression." (PMID 37781188, 2023). "However, in the present study no significant coevolution was found between IL-6, TNF-α, BDNF, and depression severity." (PMID 34841285, 2021). "In older adults, elevations in IL-6 and C-reactive protein (CRP) have been documented even prior to the onset of syndromal depression, suggesting that they are a “trait” rather than a “state” marker of depression." (PMID 34066585, 2021). "Regarding the entire sample in our results, we could not find a significant correlation between depression scores in DIKJ and TNF-α or IL-6-levels at baseline." (PMID 34204400, 2021).
depression (continued). "Moreover, other inflammatory markers that were found to be relevantly involved in depression such as IL-1 and TNF-α were not available from the LIFE-Adult-Study; for this reason, only IL-6, CRP and WBC were examined in this work." (PMID 34201276, 2021). "Nevertheless, human studies assessing the relationship between serum levels of pro-inflammatory cytokines (i.e., IL-6, INF-γ, TNF-α) and the anti-inflammatory lactoferrin with indicators of TRP metabolism in a large group of individuals with signs of depression are still lacking." (PMID 33312105, 2020). "In general, TRD and drug-free patients had similarly increased levels of inflammation-related genes: this applied to both the genes that had been measured before in depression (IL1-beta, IL-6, TNF-alpha and MIF) and those never measured before (A2M, CRP, P2RX7, CCL2 and STAT1)." (PMID 32699209, 2020). "However, we only tested one marker of inflammation (CRP) because other robust markers of inflammation (e.g., IL-6 and TNF-α) are not available in the NHANES data set, and the current utility of these inflammatory markers in depression is unclear." (PMID 30524737, 2018). "However, Karaoulanis and colleagues found that serum levels of three cytokines (IL-6, TNF-α, and IL-10) did not significantly change in relation to hot flashes in perimenopausal women with depression." (PMID 28846735, 2017). "In this study, we found that ketamine could attenuate decreased serum levels of IL-1β and IL-6, but not TNF-α level, in rats with depression-like phenotype." (PMID 28600519, 2017). "Materials and Methods: Inflammatory markers (IL-6, IL-1α, and TNF-α) were measured in a sample of 92 patients hospitalized at the Socola Institute of Psychiatry in Iasi, Romania, and compared to a control group with no depression or inflammatory conditions (n = 76)." (PMID 39595067, 2024). "However, in the current study, the stimulated production of IL-6 was not elevated in depression, whereas increased serum/plasma IL-6 was established in MDD/MDE in reviews and a meta-analysis, while an early study found increased IL-6 in culture supernatant of PBMCs." (PMID 35455402, 2022). "For instance, high levels of interleukin-6 and 8, two key mediators of the SASP, are found to be significantly elevated in the CSF of aged women with clinical depression compared to those without depression, suggesting a role of these pro-inflammatory factors in producing psychiatric symptoms." (PMID 31727161, 2019).
diabetes (1,999 papers, 2006 to 2026). "This study also further explored the independent risk factors for LFCN injury and found that diabetes, patient body mass index (BMI), and early postoperative levels of IL-6 and TNF-α were closely related to LFCN injury." (PMID 40236989, 2025). "Diabetes pathogenesis can be linked to inflammation through IL-6 elevation, which also contributes to impaired insulin signaling and hepatic glucose output." (PMID 41011232, 2025). "This is the first study based on two frameworks (cross-sectional and longitudinal) to assess the association between diabetes and biomarkers of AD and the mediating role of IL-6." (PMID 40606939, 2025). "Diabetes causes glucotoxicity and lipotoxicity, which elevate the production of L-1β, IL-6, and IL-8 within the pancreatic islets." (PMID 39812539, 2025). "Beyond diabetes, systemic inflammatory diseases such as rheumatoid arthritis share overlapping cytokine profiles (e.g., elevated IL-6 and TNF-α) and are associated with increased periodontal and cardiovascular risk." (PMID 41007869, 2025). "Diabetes is associated with persistent low-grade inflammation, characterized by elevated levels of proinflammatory cytokines such as IL-1β, IL-6, and TNF-α." (PMID 41438123, 2025). "Background/Objectives: Inflammation is a hallmark of diabetes, with interleukin-6 (IL-6) emerging as a key mediator linking immune activation with metabolic regulation." (PMID 41010714, 2025). "Logistic regression incorporating all biomarkers yielded a modest predictive accuracy of 33.3%, with CRP emerging as the most influential predictor of diabetes risk, followed by IL-6." (PMID 41523554, 2025). "IL-6 primarily reflects the severity of inflammation, the link between inflammation and diabetes, and the prevalence of associated diabetic complications." (PMID 41302503, 2025). "Serum level of N6CA was positively associated circulating interleukin-6, complication of type 2 diabetes mellitus, and hypertension." (PMID 40681942, 2025). "Studies have shown that patients with type 2 diabetes exhibit increased concentrations of C-reactive protein (CRP) and interleukin-6 (IL-6), both of which are associated with a higher risk of diabetes-related complications." (PMID 41030257, 2025). "Type 2 diabetes mellitus is strongly associated with elevated levels of IL-6, leptin, CRP, and TNF-α." (PMID 41155523, 2025). "TNFR1 mediated 56.5% of the positive association between diabetes and IL-10 independently of IL-6, while IL-6 mediated 20.8% of the association independently of TNFR1." (PMID 41280118, 2025). "In diabetic conditions, MGO causes elevated levels of IL-6 and other cytokines such as IL-1β and therefore inflammation in patients, contributing to the pathology of diabetes." (PMID 41000474, 2025). "For example, adipocytes are cells with high metabolic activity that produce adipokines such as C-reactive protein, tumour necrosis factor alpha (TNFα) and interleukin-6 (IL-6), which increase the risk of diabetes and cardiovascular disease." (PMID 40142230, 2025). "Apart from classical inflammatory cytokines (such as TNF, IL1, or IL6), new markers of inflammation have arisen as important pathogenic mediators for the progression of chronic kidney disease in diabetes (i.e., IL-1 beta, caspase 1-dependent NLRP3)." (PMID 38921685, 2024). "Sustained high PAL can induce adaptations in middle-aged and older adults, such as weight loss, increased GLUT4 and interleukin-6 expression, and reduction in cardiovascular diseases, all contributing to reduced diabetes incidence." (PMID 39185125, 2024). "It is associated with various cytokines, including TNF‐α and IL‐6, which are linked to diabetes development." (PMID 39035847, 2024). "An investigation of the potential correlation between the severity of fatty liver disease and changes in the secretion patterns of IL-6 trans-signaling co-receptors in NAFLD linked with diabetes was the focus of separate research." (PMID 38535313, 2024).
diabetes (continued). "In multivariate analysis, the significantly related risk factors included age, diabetes, chronic kidney disease, vaccination status, interleukin-6, procalcitonin, leukocytes, platelets, D-dimer, and activated partial thromboplastin time." (PMID 38822405, 2024). "Elevated blood glucose in uncontrolled diabetes has been attributed to facilitate a low-grade systemic inflammation by causing the elevation of proinflammatory cytokines such as interleukin-6 and C reactive proteins." (PMID 38963109, 2024). "Healing complications are reported to occur more frequently in patients with inflammatory disorders, which are often associated with increased circulating IL-6 levels, including osteoporosis, rheumatoid arthritis, and diabetes." (PMID 39166608, 2024). "We examined levels of key factors that are associated with proinflammation and significantly altered in diabetes (IL1β, IL6 and IL10) and that are associated with angiogenesis (VEGF-A) in M1 macrophages." (PMID 38270651, 2024). "Multivariate logistic regression analysis revealed significant associations between gender, diabetes mellitus history, smoking history, LPa, IL-6, ceramide (d18:1/16:0) and ACS." (PMID 38218768, 2024). "While diabetes, particularly in poorly controlled cases, is associated with elevated inflammatory markers like IL-6 and TNF-α, the impact on implant survival appears to be minimal when glycemic levels are well-regulated." (PMID 39867008, 2024). "In contrast, an SNP in the promoter region of IL-6 (174G > C), enhancing IL-6 production in response to inflammatory stimuli, increases the risk of Alzheimer’s disease, non-insulin-dependent diabetes mellitus, and juvenile chronic arthritis." (PMID 38732533, 2024). "In the Women’s Health Study, there was an increased risk of developing diabetes for those in the highest vs. lowest quartile of baseline IL-6 (RR: 2.3 [0.9, 5.6]) and CRP (RR: 4.2 [1.5 – 12.0])." (PMID 38665261, 2024). "In the Sharma study, they found a statistically significant association between the IL-6-597 gene polymorphism and a chronic periodontitis with type 2 diabetes mellitus (CHPDM) group." (PMID 38396821, 2024). "Several important reviews highlight the critical role of inflammatory factors, especially interleukin-6 (IL-6), in the development of type 2 diabetes mellitus (T2DM) and its associated kidney diseases." (PMID 39749325, 2024). "The risk prediction nomogram of age, diabetes, chronic kidney disease, vaccination status, procalcitonin, leukocytes, lymphocytes, interleukin-6 and D-dimer were included for early identification of high-risk patients with Long COVID." (PMID 38822405, 2024). "Interleukin-6: omentin-1 ratio of ≤0.26 was associated with kidney protection among patients with type 2 diabetes mellitus." (PMID 39131026, 2024). "There was insufficient evidence to suggest that RHI, age, race, current smoker, preexisting hypertension or diabetes, IL-6, or hs-CRP were associated with sex." (PMID 39066250, 2024). "The risk estimates calculated demonstrated that diabetes mellitus patients with an IL-6: omentin-1 ratio ≥0.26 had significantly higher odds, with an odds ratio of 3.97, for developing DN." (PMID 39131026, 2024). "As for the analysis of interleukin-6 polymorphisms, it appears that the G allele is associated with the occurrence of pregnancy complications, either in the form of diabetes mellitus or in the form of preeclampsia." (PMID 38893732, 2024). "Risk assessment demonstrated that type 2 diabetes mellitus patients with an interleukin-6: omentin-1 ratio ≥0.26 had significantly higher odds, with an odds ratio of 3.97, for developing diabetic nephropathy, which was statistically significant." (PMID 39131026, 2024). "A number of studies demonstrated that high levels of hs-CRP and IL-6 are associated with high blood pressure, independently of diabetes." (PMID 39404426, 2024). "IL-6, associated with higher albuminuria, has been reported in db/db mice and patients with diabetes." (PMID 36776877, 2023).
diabetes (continued). "A statistically significant positive association was found between diabetes’ duration and the percentages of CD11b+IL-6+ PBMCs in unstimulated culture condition (p = 0.04, R2 = 0.122, B = 0.827)." (PMID 36766809, 2023). "Epidemiologic studies have indicated a positive correlation between the raised plasma level of inflammatory cytokines, such as tumor necrosis factor α (TNF-α) and interleukin-6 (IL-6), with a higher risk of diabetes." (PMID 37298715, 2023). "The present study investigated to explore the association of interleukin-6 and uric acid in patients with type 2diabetes mellitus and coronary artery disease." (PMID 38250529, 2023). "Both SC and macrophages secrete IL‐6 upon injury, and has been associated with several age‐related diseases such as multiple sclerosis, Alzheimer's disease, diabetes, and systemic lupus." (PMID 37860842, 2023). "Patients with diabetes with low IL-6 levels showed a marginally increased risk of AVF dysfunction (HR = 4.36, 95% CI = 0.87–21.94, p = 0.074)." (PMID 36675812, 2023). "This study reported a weak indirect effect for the association between low social support at work and diabetes among females though IL-6 plasma concentration." (PMID 36981836, 2023). "A longer duration of diabetes was associated with higher levels of IL-6 by CD11b+ cells which suggests a relationship with the disease and their potential to be used as biomarkers of DR." (PMID 36766809, 2023). "Hyperglycemia was significantly associated with a greater risk of frailty in the adjusted model controlling for BMI, IL-6, and chronic morbidities such as diabetes mellitus, osteoarthritis, coronary heart disease, stroke, and COPD." (PMID 35795135, 2022). "Diabetes also has a bidirectional relationship with lean body mass loss through low-grade systemic inflammation, which can be marked by interleukin-6 (IL-6), tumor necrosis factor-alpha (TNF-alpha), C-reactive protein (CRP), and white blood cell count." (PMID 36362539, 2022). "After the initiation of self-damaging reactions, all mitochondrion-derived oxidative stress, diabetes-associated DNA damage and increased specific inflammatory cytokines (such as interleukin 6, and C-reactive protein) contribute to microvascular abnormalities." (PMID 35529431, 2022). "Interleukin-1 and interleukin-6, two pro-inflammatory cytokines, have been linked to greater levels of inflammation in people with diabetes." (PMID 35978734, 2022). "CVD was significantly associated with older age, diabetes mellitus, low levels of hemoglobin, creatinine, the higher half of IL-6, past history of CVD, use of ACE-Is or ARBs, and use of β blockers in the unadjusted Cox proportional hazards model." (PMID 35155493, 2022). "sedentary group is in line with previous studies, which suggested that patients with elevated levels of CRP and pro-inflammatory cytokines such as TNF-α, IL-6 are at increased risk of diabetes, atherosclerosis, hypertension and other cardiovascular diseases." (PMID 36434695, 2022). "STZ-induced diabetes was associated with increased levels of blood glucose, ROS, and IL-6 and decreased levels of IL-2, IL-7, IL-4, and GSH." (PMID 35554836, 2022). "We found evidence of a positive association with fasting insulin, 2-h insulin, incident diabetes and IL-6—with overall medium study quality." (PMID 35544519, 2022). "IL6 is mainly produced at sites of acute and chronic inflammation, and it has been implicated in various inflammation-related disease states, including diabetes and systemic rheumatoid arthritis." (PMID 36105284, 2022). "The decreased number of CD3+CD4+ T cells and increased level of IL-6 were independent risk factors of cardiac injury, which can be promoted by the presence of diabetes." (PMID 36123740, 2022). "Elevated blood levels of IL-6 have been moderately associated with diabetes and dyslipidemia, and significant predictive value has been shown for myocardial infarction and death related to coronary artery disease." (PMID 36143268, 2022).